PRKACA (protein kinase cAMP-activated catalytic subunit alpha)
Description:
Phosphorylates a large number of substrates in the cytoplasm and the nucleus. Phosphorylates CDC25B, ABL1, NFKB1, CLDN3, histone H1.4 (H1-4), PSMC5/RPT6, PJA2, RYR2, RORA, SLC6A6, SOX9, UHRF1 and VASP. Regulates the abundance of compartmentalized pools of its regulatory subunits through phosphorylation of PJA2 which binds and ubiquitinates these subunits, leading to their subsequent proteolysis. RORA is activated by phosphorylation. Required for glucose-mediated adipogenic differentiation increase and osteogenic differentiation inhibition from osteoblasts. Involved in chondrogenesis by mediating phosphorylation of SOX9 (By similarity). Involved in the regulation of platelets in response to thrombin and collagen; maintains circulating platelets in a resting state by phosphorylating proteins in numerous platelet inhibitory pathways when in complex with NF-kappa-B (NFKB1 and NFKB2) and I-kappa-B-alpha (NFKBIA), but thrombin and collagen disrupt these complexes and free active PRKACA stimulates platelets and leads to platelet aggregation by phosphorylating VASP. Prevents the antiproliferative and anti-invasive effects of alpha-difluoromethylornithine in breast cancer cells when activated. RYR2 channel activity is potentiated by phosphorylation in presence of luminal Ca(2+), leading to reduced amplitude and increased frequency of store overload-induced Ca(2+) release (SOICR) characterized by an increased rate of Ca(2+) release and propagation velocity of spontaneous Ca(2+) waves, despite reduced wave amplitude and resting cytosolic Ca(2+). PSMC5/RPT6 activation by phosphorylation stimulates proteasome. Negatively regulates tight junctions (TJs) in ovarian cancer cells via CLDN3 phosphorylation. NFKB1 phosphorylation promotes NF-kappa-B p50-p50 DNA binding. Acts as a key inhibitor of smoothened signaling pathway by mediating phosphorylation of GLI (GLI1, GLI2 and GLI3) transcription factors in absence of hedgehog (DHH, IHH or SHH) morphogens: GLI phosphorylation promotes their processing and prevents transcriptional activation of smoothened target genes. GLI transcription factor phosphorylation is inhibited by interaction of PRKACA with SMO which sequesters PRKACA at the cell membrane. Also inhibits the smoothened signaling pathway in embryonic development by catalyzing phosphorylation of OFD1 in ciliogenesis. Prevents meiosis resumption in prophase-arrested oocytes via CDC25B inactivation by phosphorylation (By similarity). May also regulate rapid eye movement (REM) sleep in the pedunculopontine tegmental (PPT) (By similarity). Phosphorylates APOBEC3G and AICDA. Phosphorylates HSF1; this phosphorylation promotes HSF1 nuclear localization and transcriptional activity upon heat shock. Acts as a negative regulator of mTORC1 by mediating phosphorylation of RPTOR. Phosphorylates AKAP19. [Isoform 2]: Phosphorylates and activates ABL1 in sperm flagellum to promote spermatozoa capacitation.
Synonyms: PKACA; CAFD1; PPNAD4
Tractability: Small molecule: a drug acting on it is in phase 1 trials; a structure with a bound ligand is known; a high-quality ligand is known; it has a high-quality binding pocket; it belongs to a druggable protein family. Antibody: UniProt places it where antibodies can reach, with high confidence; its Gene Ontology location is reachable by antibodies, with high confidence. PROTAC: ubiquitination databases record sites on it; its protein half-life has been measured; a small molecule that binds it is known.
Target class: Kinase; AGC protein kinase PKA family; Protein Kinase; AGC protein kinase group; Enzyme
Safety:
Unwanted effects reported when the protein is acted on. In parentheses: how it was acted on, where the effect was seen, and who reports it.
cardiac arrhythmia (cardiovascular system; source: Lamore et al. (2017))
Gene: Protein-coding gene on chromosome 19 (14,091,688 to 14,118,084, reverse strand). Ensembl gene ENSG00000072062.
Subcellular location: Cytoplasm; Cell membrane; Membrane; Nucleus; Mitochondrion; Cell projection, cilium, flagellum (Isoform 2); Cytoplasmic vesicle, secretory vesicle, acrosome
Subcellular location (Human Protein Atlas): Cytosol; Basal body; Cytokinetic bridge; Microtubules; Primary cilium
Pathways (Reactome):
Signal Transduction: DARPP-32 events; Degradation of GLI1 by the proteasome; Degradation of GLI2 by the proteasome; GLI3 is processed to GLI3R by the proteasome; GPER1 signaling; Hedgehog 'off' state; MAPK6/MAPK4 signaling; PKA activation; PKA-mediated phosphorylation of CREB; VEGFA-VEGFR2 Pathway
Cell Cycle: AURKA Activation by TPX2; Loss of Nlp from mitotic centrosomes; Loss of proteins required for interphase microtubule organization from the centrosome; Recruitment of NuMA to mitotic centrosomes; Recruitment of mitotic centrosome proteins and complexes; Regulation of PLK1 Activity at G2/M Transition
Metabolism: Glucagon-like Peptide-1 (GLP1) regulates insulin secretion; PKA activation in glucagon signalling; PKA-mediated phosphorylation of key metabolic factors; Regulation of glycolysis by fructose 2,6-bisphosphate metabolism; Regulation of insulin secretion; Triglyceride catabolism
Disease: ADORA2B mediated anti-inflammatory cytokines production; FCGR3A-mediated IL10 synthesis
Immune System: CD209 (DC-SIGN) signaling; Interleukin-3, Interleukin-5 and GM-CSF signaling; Rap1 signalling
Developmental Biology: RET signaling; ROBO receptors bind AKAP5
Transport of small molecules: HDL assembly; Vasopressin regulates renal water homeostasis via Aquaporins
Cellular responses to stimuli: High laminar flow shear stress activates signaling by PIEZO1 and PECAM1:CDH5:KDR in endothelial cells
Hemostasis: Factors involved in megakaryocyte development and platelet production
Metabolism of proteins: Mitochondrial protein degradation
Muscle contraction: Ion homeostasis
Neuronal System: CREB1 phosphorylation through the activation of Adenylate Cyclase
Organelle biogenesis and maintenance: Anchoring of the basal body to the plasma membrane
Gene Ontology:
Molecular function: cAMP-dependent protein kinase activity; histone H1-4S35 kinase activity; potassium channel inhibitor activity; protein binding; protein kinase A regulatory subunit binding; protein kinase binding; protein serine kinase activity; protein serine/threonine kinase activity; protein serine/threonine/tyrosine kinase activity; channel activator activity; ATP binding; magnesium ion binding; manganese ion binding; protein domain specific binding; protein kinase activity
Biological process: adenylate cyclase-inhibiting G protein-coupled receptor signaling pathway; cellular response to glucose stimulus; cellular response to heat; intracellular potassium ion homeostasis; mRNA processing; negative regulation of protein localization to chromatin; negative regulation of smoothened signaling pathway; negative regulation of TORC1 signaling; positive regulation of cholesterol biosynthetic process; positive regulation of phagocytosis; positive regulation of protein localization to plasma membrane; protein phosphorylation; regulation of bicellular tight junction assembly; regulation of microtubule cytoskeleton organization; regulation of osteoblast differentiation; regulation of proteasomal protein catabolic process; adenylate cyclase-activating G protein-coupled receptor signaling pathway; cell communication by electrical coupling involved in cardiac conduction; cellular response to epinephrine stimulus; cytokine-mediated signaling pathway; high-density lipoprotein particle assembly; mitochondrial protein catabolic process; negative regulation of interleukin-2 production; positive regulation of calcium-mediated signaling; positive regulation of insulin secretion; and 17 more
Cellular component: axoneme; cAMP-dependent protein kinase complex; centrosome; cytoplasm; extracellular exosome; nuclear speck; nucleus; perinuclear region of cytoplasm; plasma membrane; plasma membrane raft; acrosomal vesicle; calcium channel complex; ciliary base; cytosol; mitochondrial matrix; mitochondrion; nucleoplasm; glutamatergic synapse; lipid droplet; membrane; motile cilium; neuromuscular junction; postsynapse; sperm flagellum
Genetic constraint (gnomAD): Loss-of-function variants: 9 observed, 46.44 expected, observed/expected ratio (o/e) 0.19, 90% interval 0.12 to 0.34. The upper end of that interval is the gene's LOEUF score, 0.34, which puts it in group 1 of 6, group 1 being the genes least tolerant of losing a copy. Missense variants: 238 observed, 465.08 expected, observed/expected ratio (o/e) 0.51, 90% interval 0.46 to 0.57. Synonymous variants: 160 observed, 183.7 expected, observed/expected ratio (o/e) 0.87, 90% interval 0.76 to 0.99.
Cancer hallmarks: escaping programmed cell death (promotes); proliferative signalling (promotes)
Homologues: Orthologues: macaque PRKACA (100% identical), dog PRKACA (99% identical), mouse Prkaca (98% identical), pig PRKACA (96% identical), rat Prkaca (94% identical), tropical clawed frog prkaca (90% identical), zebrafish prkacab (89% identical), zebrafish prkacba (83% identical), chimpanzee PRKACA (73% identical), Drosophila melanogaster Pka-C2 (44% identical), Drosophila melanogaster CG12069 (43% identical), Drosophila melanogaster Pkg21D (41% identical), and 1 more. Paralogues in human: PRKACB (90% identical), PRKACG (82% identical), PRKX (48% identical), PRKG2 (45% identical), PRKG1 (44% identical).
Diseases named in the same sentence as PRKACA in open-access papers:
PRKACA is named in the same sentence as 110 diseases in open-access papers, as found by Europe PMC text mining. Sharing a sentence is not in itself a finding about the gene and the disease. The quoted sentences say what the papers report.
adenoma (19 papers, 2015 to 2026). A neoplasm arising from the epithelium. "Within T-DNA, somatic variants were identified in 53% of adenomas: PRKACA in 2/7 CPA-CS, CTNNB1 in 3/5 CPA-MACS and 1/7 CPA-CS, KCNJ5 in 2/5 APA and CACNA1D in 1/5 APA." (PMID 39891827, 2025). "Cortisol-producing adenomas causing either Cushing's syndrome, particularly those with PRKACA or GNAS somatic mutations associated with a more severe phenotype, or mild autonomous cortisol secretion (MACS) are more commonly observed in women." (PMID 40296186, 2025). "PRKACA mutations in these adenomas have been demonstrated to have a limited impact on cell proliferation and tumor growth." (PMID 39458904, 2024). "Previous clinical studies have consistently shown that somatic mutations in PRKACA, which encodes the catalytic subunit Cα, are predominantly associated with cortisol-producing adenomas exhibiting overt symptoms of CS." (PMID 39010034, 2024). "Most cortisol-producing adenomas with overt Cushing’s syndrome are associated with mutations in the cAMP/PKA pathway (PRKACA and GNAS), which are less frequency detected in patients with PACS or ACS." (PMID 37223045, 2023). "PRKACA somatic-activating mutations are the main alterations in unilateral cortisol-producing adenomas." (PMID 32783015, 2020). "Mutations in the gene encoding the alpha catalytic subunit of protein kinase A (PRKACA) have been reported in 30-65% of adenomas causing overt CS 115,116." (PMID 30208164, 2018). "Somatic mutations in protein kinase A catalytic α subunit (PRKACA) were found to be causative for 30–40% of cortisol-producing adenomas (CPA) of the adrenal gland, rendering PKA signalling constitutively active." (PMID 28250426, 2017). "Furthermore, by introducing a hotspot pathogenic variant (PRKACA L206R) identified in Cushing’s syndrome, we achieved the organoid disease modeling of cortisol-producing adenomas." (PMID 41106389, 2025). "However, in 2016, PRKACA somatic mutations were first identified in aldosterone-producing adenomas, and patients with p.Leu206Arg mutations presented with subclinical Cushing syndrome (SCS)." (PMID 39010034, 2024). "Notably, PRKACA mutations are rare in aldosterone-producing adenomas (APAs), and their precise mechanistic role in APAs remains elusive." (PMID 39010034, 2024). "Additionally, 99% of adenomas bearing mutations in cAMP/PKA pathway-related genes (PRKACA, GNAS, or PRKAR1A) displayed high StAR expression." (PMID 27606678, 2016). "Somatic activating PV in PRKACA, the gene encoding the catalytic subunit of PKA, have also been described in cortisol-producing adenomas." (PMID 41816209, 2026). "PRKACA is the gene encoding the catalytic subunit of PKA and has been repeatedly implicated in cortisol-producing adenomas (CPAs)." (PMID 39010034, 2024). "PRKACA-altered glucocorticoid-producing adenomas were observed in younger individuals with florid Cushing syndrome and frequently presented with smaller tumor size than that of PRKACA-wild-type glucocorticoid-producing adenomas." (PMID 29594118, 2018). "In a cohort of PRKACA-wild-type adenomas, glucocorticoid-producing CTNNB1-mutant adrenocortical adenomas were more likely to present with subclinical Cushing syndrome." (PMID 29594118, 2018). "Altogether these results demonstrate that PRKACA mutations constitutively activate PKA leading to cortisol-producing adenomas, thereby suggesting that PRKACA is a main contributor to adrenocortical tumorigenesis." (PMID 26042218, 2015). "Combined with genetic manipulation, like introducing a hotspot PV of PRKACA via lentiviral transfection to mimic cortisol-producing adenomas, these organoids could serve as an ideal tool for drug screening." (PMID 41106389, 2025). "Somatic activating mutations of protein kinase A catalytic subunit (PRKACA) has been implicated in up to 50% of patients with adenomas with clinical Cushing’s syndrome, but not in adenomas producing less cortisol." (PMID 32266384, 2020).
adenoma (continued). "Conversely, no concomitant CTNNB1, PRKACA, PRKAR1A or GNAS somatic variant (classically met in cortisol-producing adenomas) with a germline ARMC5 alteration has been yet reported to our knowledge." (PMID 39910635, 2025).
fibrolamellar hepatocellular carcinoma (19 papers, 2018 to 2026). A distinctive type of liver cell carcinoma that arises in non-cirrhotic livers and is seen predominantly in young patients. "PRKACA is also involved in gene fusion, and fusion genes containing PRKACA have been detected in fibrolamellar carcinoma and intraductal eosinophilic papillary tumors of the pancreas." (PMID 36911522, 2023). "The data in this study shows that the detection of PRKACA rearrangement has a sensitivity of 99% for the diagnosis of fibrolamellar carcinoma." (PMID 28862261, 2018). "Follow-up qPCR confirmed a 2–5-fold increase in PRKACA mRNA in this case, compared to 4 randomly selected fibrolamellar carcinoma cases with typical FISH patterns." (PMID 28862261, 2018). "Each of the eight (100%) fibrolamellar carcinomas in the second tissue microarray was positive for PRKACA rearrangement in the typical pattern." (PMID 28862261, 2018). "A fusion gene of DNAJB1/HDJ1 and PRKACA (protein kinase cAMP-activated catalytic subunit alpha), resulting from an ~400 kb of in-frame deletion on chromosome 19, is found in nearly all cases of fibrolamellar hepatocellular carcinoma (FL-HCC)." (PMID 34948322, 2021). "In conclusion, PRKACA FISH is a powerful tool to confirm the diagnosis of fibrolamellar carcinoma." (PMID 28862261, 2018). "All but one case of typical fibrolamellar carcinoma was positive for PRKACA rearrangement." (PMID 28862261, 2018). "The fusion of PRKACA and DNAJB1 is dominant and oncogenic in fibrolamellar hepatocellular carcinoma (FLC), while the DNAJB1-PRKACA or ATP1B1-PRKACB fusion is also detected in pancreatobiliary neoplasms." (PMID 38233872, 2024). "The DNAJB-PRKACA gene fusion, created by the fusion of a subunit of the HSP40 complex (DNAJB) and the catalytic subunit of protein kinase A (PRKACA), creates a fusion kinase and drives fibrolamellar hepatocellular carcinoma, and PTMs of this kinase could impact cancer progression." (PMID 39433125, 2024). "PRKACA FISH was positive for rearrangement in 102 of 103 (99%) typical fibrolamellar carcinomas, 9 of 12 ‘possible fibrolamellar carcinomas’ and 0 of 8 cases ‘unlikely to be fibrolamellar carcinomas’." (PMID 28862261, 2018).